PARP14 (poly(ADP-ribose) polymerase family member 14)
Diseases named in the same sentence as PARP14 in open-access papers (continued):
Sharing a sentence is not in itself a finding about the gene and the disease.
insulinoma (1 paper, 2019). "In our study, we used mouse αTC1.6 glucagonoma and βTC1 insulinoma cells as experimental models to verify the molecular basis of the involvement of PARP-14 in the JNK pathway in pancreatic inflammatory state." (PMID 31130919, 2019).
multiple sclerosis (1 paper, 2025). A progressive autoimmune disorder affecting the central nervous system resulting in demyelination. "The disease-specific pathway of multiple sclerosis (MS) signaling was upregulated across all YWH groups, marked by shared upregulation of interferon-responsive genes such as PARP9 and PARP14, indicating persistent immune activation despite viral suppression." (PMID 40862746, 2025).
rectal cancer (1 paper, 2025). A primary or metastatic malignant neoplasm that affects the rectum. "We then explored the distribution of low and high fold of expression after CRT of PARP9, PARP12, PARP13, and PARP14 in both tumor and adjacent normal tissue sample groups from rectal cancer patients." (PMID 40646573, 2025). "The high pre-treatment PARP9 levels and a blunted post-treatment increase in both PARP9 and PARP14 expression emerged as independent predictors of poorer overall survival in rectal cancer patients." (PMID 40646573, 2025). "Surprisingly, our findings highlighted the potential clinical significance of PARP9 and PARP14 in rectal cancer." (PMID 40646573, 2025). "Overall, these findings suggest that PARP9 and PARP14 expression profiles could be important prognostic factors for survival in rectal cancer patients." (PMID 40646573, 2025). "Elevated pre-treatment PARP9 expression levels and a blunted post-treatment increase in PARP9 and PARP14 expression predicted poor overall survival in rectal cancer patients, while PARP13 emerged as the most significant discriminator between tumor and healthy tissue." (PMID 40646573, 2025). "Notably, high pre-treatment PARP9 expression and a weaker post-treatment increase in PARP9 and PARP14 expression emerged as independent predictors of worse overall survival in rectal cancer patients." (PMID 40646573, 2025).
rectal tumors (1 paper, 2025). "Taken together, this study demonstrates that CRT significantly increases the expression of PARP9, PARP12, PARP13 and PARP14, specifically in rectal tumor tissue." (PMID 40646573, 2025). "Finally, we demonstrated that chemoradiotherapy significantly upregulates the expression of PARP9, PARP12, PARP13 and PARP14 exclusively within rectal tumor tissues." (PMID 40646573, 2025).
retinal degeneration (1 paper, 2017). Degeneration of the retina. "Our transcriptomic data also revealed an increase in a number of non-apoptotic pathway genes that have been implicated in retinal degeneration, such as a number of poly-ADP-ribose-polymerases (PARP9, PARP14, PARP15) and histone deacetylases (HDAC7, HDAC10, HDAC11)." (PMID 29263354, 2017).
uterine disease (1 paper, 2022). "Pregnancy regulated genes downstream of AIRE in cows following uterine infection are all upregulated (EIF2AK2, IFI44, HERC6, PARP14, TNFSF10), suggesting the dysregulated expression of these genes could be important for pregnancy establishment following uterine disease." (PMID 35358206, 2022).
cancer (34 papers, 2015 to 2025). A tumor composed of atypical neoplastic, often pleomorphic cells that invade other tissues. "•PARP9 and DTX3L regulate PARP14 protein levels therefore depleting PARP9, DTX3L or PARP14 mRNA results in loss of PARP14 protein and a reduction in cancer cell survival through a loss of proliferation and increase in apoptosis." (PMID 38182103, 2024). "This study aimed to characterise the interactions and structural requirements of the complex of PARP9/DTX3L and PARP14 which is implicated in survival of several cancer cell types." (PMID 38182103, 2024). "Our current data underline the importance of PARP14, not only in IL-4-induced M2 but also in cancer-cell-induced TAM polarization." (PMID 38612413, 2024). "Among these RBPs, PARP14 is widely associated with immune checkpoints, the tumor microenvironment, and immune-infiltrating cells in various cancer types." (PMID 37628671, 2023). "PARP14 is associated with a multitude of disease states, including; cancer, atherosclerosis and the inflammatory response to allergens." (PMID 35096828, 2021). "PARP14 has been implicated in cancer progression across multiple tumor types." (PMID 40741921, 2025). "•PARP9 and PARP14 are lesser studied ADP-ribosyltransferases implicated in cancer cell survival." (PMID 38182103, 2024). "PARP14 is involved in multiple signaling pathways linked to cancer, inflammation, and infection, and pharmacological modulation of PARP14 activities may prove as a suitable therapeutic strategy." (PMID 37507011, 2023). "Below, we discuss examples of MARylating PARPs – namely PARP3, PARP6, PARP7, PARP9–12, PARP14 and PARP16 – that have been linked to cancer progression and survival." (PMID 40741921, 2025). "Specifically, it has been described that the interleukin-4 (IL4)-mediated cellular response requires PARP14 activity on STAT6 to bind to the target promoters of the IL4-mediated inflammatory cascade in cancer, inflammation, and immune response." (PMID 41463260, 2025). "PARP14 is involved in signalling pathways with relevance to cancer, inflammation, DNA repair, gene transcription, and cell death in humans." (PMID 39823074, 2025). "Much attention has been given to pro-tumour roles of PARP9 and PARP14 in a variety of cancer types, particularly as some tumours have elevated levels of expression of transcript and protein." (PMID 38182103, 2024). "PARP14/BAL2 is a large multidomain enzyme involved in signaling pathways with relevance to cancer, inflammation, and infection." (PMID 37507011, 2023). "And it was also validated that the mRNA expression of PARP14 in tumor tissues was significantly increased when compared to the matched para-cancer tissues." (PMID 37650946, 2023). "It was suggested that PARP14 performs different roles in tumor development and progression of different cancer types." (PMID 36814782, 2023). "Identifying how MARylation regulates these substrates, and the changes in binding partners induced by the modification, is likely to reveal critical mechanisms employed by PARP10 and PARP14 in cancer." (PMID 36814782, 2023). "Here the authors report that PARP14 is upregulated in chronic IFNγ-treated cancer cell models and that its inhibition restores response to anti-PD-1 therapy in preclinical cancer models." (PMID 37752135, 2023). "Here, we outline some of the key roles of PARP10 and PARP14 in modulating DNA damage repair, and how PARP10/PARP14 status affects cancer development and the response to chemotherapeutics." (PMID 36814782, 2023). "In order to explore the role of PARP14 in the tumor immunity of patients with various cancers, we calculated three ESTIMATE indices in each sample to evaluate the proportions of stromal and immune cells." (PMID 37628671, 2023). "We highlight the roles of PARP10 and PARP14 in cancer progression and response to chemotherapeutics and briefly discuss currently known PARP10 and PARP14 inhibitors." (PMID 36814782, 2023).
cancer (continued). "Here, we highlighted the roles of MARylation, and in particular those of PARP10 and PARP14, in DNA repair and cancer." (PMID 36814782, 2023). "The results showed that PARP14 was positively correlated with immune infiltration in 26 cancers with r-values greater than 0.3." (PMID 37628671, 2023). "Chiefly among those is the identity of the relevant substrates of PARP10 and PARP14 in genome stability and cancer cell proliferation and tumorigenesis." (PMID 36814782, 2023). "Firstly, we investigated the correlation between PARP14 and other immune checkpoints (ICs) in pan-cancer data from TCGA." (PMID 37628671, 2023). "Inhibitors of tankyrases (the selective inhibitor STP1002 and the dual PARP1/PARP2 and TNKS1/TNKS2 inhibitor E7449), PARP7 (RBN-2397), and PARP14 (RBN-31430) are currently undergoing clinical trials for treatment of cancer and inflammatory diseases." (PMID 37832523, 2023). "In contrast, PARP14 also alleviated cancer by promoting genomic stability by improving homologous recombination and DNA repair in HeLa cells." (PMID 35679255, 2022). "We found expression of genes involved in cancer proliferation (PARP14, VMP1, APOE) in the mBc4 cluster." (PMID 36153593, 2022). "In support of targeting PARP14 to treat cancer, an inhibitor of PARP14, RBN012759, was shown to lead to an inflammatory response in tumour explants, similarly to that induced by immune checkpoint inhibitors." (PMID 35096828, 2021). "In fact, targeting PARP14 has been proposed as a possible therapeutic approach for not only MM but also multiple cancer types, and PARP14 inhibitors are currently being developed." (PMID 34976832, 2021). "PARP14 catalytic inhibitors are currently being developed and targeting PARP14 has been proposed as a possible therapeutic approach for multiple cancer types." (PMID 32542389, 2020). "Plenty of literature indicated that PARP14 is not only related to cancers but also to other diseases, such as atherosclerosis and allergic inflammation." (PMID 30890936, 2019). "Our work suggests that PARP14 inhibitors can potentiate genotoxic chemotherapy by blocking HR DNA repair and rendering cancer cells hypersensitive to DNA damage." (PMID 25753673, 2015). "Such an effect was also observed when we silenced PARP14 in other cancer cell types and treated them with doxorubicin." (PMID 26258887, 2015). "PARP14 is a macrodomain-containing MART that has been implicated in stress responses and cancer." (PMID 39760726, 2025). "Specifically, PARP14 silencing in different tumor cell lines led to cell cycle arrest and proliferation inhibition in a manner dependent on the cell cycle protein Cyclin D1, which is overexpressed in various cancer types." (PMID 41463260, 2025). "Notably, PARP14 inhibition suppressed the Warburg‐like glycolysis shift in inflamed chondrocytes, aligning with its role in cancer metabolism." (PMID 41194652, 2025). "Finally, since both PARP10 and PARP14 represent potential targets for cancer therapy, extensive characterization of PARP10 and PARP14 inhibitors in clinical settings is needed to determine therapeutic efficacy of these inhibitors." (PMID 36814782, 2023). "In addition, the regulation of PARP10 and PARP14 activity in normal and cancer cells, as well as the mechanisms of their subcellular localization, particularly their recruitment to DNA, is of significant interest." (PMID 36814782, 2023). "Hence, our findings provide evidence for the crucial involvement of the identified RBPs and emphasize the critical role of PARP14 in regulating cancer immunity." (PMID 37628671, 2023). "This makes targeting PARP14 a promising avenue for developing cancer therapeutics." (PMID 35096828, 2021). "This study provided a mechanistic link between PARP14, cancer cell apoptosis, and metabolism." (PMID 34976832, 2021). "Recent evidence has highlighted the role of PARP-14 in cancer and in many other diseases." (PMID 31130919, 2019).
cancer (continued). "In addition to the transcriptional functions, PARP14 plays crucial roles in the metabolic control of cancer cells." (PMID 30991935, 2019). "This study indicates that PARP14 inhibition and other undiscovered gene mutations beyond BRCA1/2 deficiency might hamper the homologous recombination repair pathway, making cancer cells more susceptible to DNA lesions." (PMID 30890936, 2019). "Moreover, previous findings have demonstrated that PARP14 might perform cancer-promoting functions in stromal cells present in the TME14,15,22." (PMID 37752135, 2023). "PARP14 could be a possible therapeutic target for cancers such as DLBCL." (PMID 30890936, 2019). "Collectively, these data suggest that PARP14 may play an oncogenic role in multiple cancer types." (PMID 26258887, 2015). "To investigate the role of PARP14 in TAM polarization, we set up an in vitro model in which the supernatant (or conditioned media, CM) was transferred from cancer cell lines to MΦs." (PMID 38612413, 2024). "Here, we summarize the current knowledge on MARylation in DNA repair and cancer, focusing on PARP10 and PARP14." (PMID 36814782, 2023). "Given their recently discovered roles in cancer development and response to chemotherapeutics, PARP10 and PARP14 represent promising clinical targets." (PMID 36814782, 2023). "This study found that cancer cell lines like RPE-1 and MCF-7 are arrested in G1 phase of cell cycle upon PARP14 depletion." (PMID 35679255, 2022). "PARP14 maintains low PKM2 activity in HCC cells by suppressing JNK1, which promotes the Warburg effect and promotes cancer cell proliferation and survival." (PMID 35652091, 2022). "Recently, Barbarulo and colleagues found that PARP14 expression was induced by the presence of JNK2, which promoted cell growth of cancer cells in multiple myeloma." (PMID 35679255, 2022). "Our work indicates that the status of the PARP14 gene in the tumor is an important determinant of the tumor response to DDR inhibitors, which are emerging as a powerful class of cancer drugs." (PMID 32542389, 2020). "PARP-14 has recently appeared to be involved in the transduction pathway mediated by JNKs (c Jun N terminal Kinases), among which JNK2 promotes cancer cell survival." (PMID 31130919, 2019). "To assess the functional role of PARP14 in cancer cells, we knocked down expression of PARP14 in HCC cells using two PARP14-specific short hairpin (sh)RNA lentiviruses (shPARP14 or shPARP14#2)." (PMID 26258887, 2015). "PARP14 is a 203 kDa multi-domain protein that is primarily known as an ADP-ribosyltransferase and is involved in a variety of cellular functions, including DNA damage, microglial activation, inflammation, and cancer progression." (PMID 40937852, 2025). "Altogether, these preliminary findings suggest that the expression of PARP9, PARP12, PARP13 and PARP14 in irradiated cells is reliant on 3-dimensional cellular microenvironment or cell type, and the PARP expression pattern may be specific to cancer cells." (PMID 40646573, 2025). "Beyond CRC, PARP14 contributes to tumorigenesis in B-cell lymphoma by inhibiting JNK1 (MAPK8) signaling, thereby preventing apoptosis, and in acute myeloid leukemia by enhancing glycolysis to support cancer cell proliferation." (PMID 40741921, 2025). "Currently, there is no consolidated data on how PARP9, PARP12, PARP13 and PARP14 affect the response to ionizing radiation in cancer cells." (PMID 40646573, 2025). "Since cancer cell survival was not dependent on PARP14 catalytic activity we postulate that PARP9/DTX3L regulates PARP14 expression and activity to promote proliferation and anti-apoptosis." (PMID 38182103, 2024). "It remains to be seen if PARP14 also plays similar roles in other types of cancer and whether the reversal of the TAM phenotype by PARP14 inhibition effectively unleashes anti-tumor effector mechanisms of the adaptive immune system." (PMID 38612413, 2024).
cancer (continued). "Despite having strong link to various pathogenic states such as inflammatory diseases and cancer, PARP10 and PARP14 inhibitors have not been well characterized." (PMID 36814782, 2023). "In hepatocellular carcinoma, PARP14 inhibits JNK1-dependent phosphorylation and activation of the pyruvate kinase M2 isoform (PKM2), thus, promoting the aerobic glycolysis (Warburg effect) of cancer cells." (PMID 30991935, 2019). "The inhibition of PKM2 activity by PARP14 may represent an additional mechanism that modulates PKM2 activity and subsequent aerobic glycolysis in cancer cells." (PMID 26258887, 2015). "Here we show that PARP14 is highly expressed in diverse solid tumours, including HCC, and positively regulates aerobic glycolysis through effects on PKM2 enzymatic activity, thus promoting survival in cancer cells." (PMID 26258887, 2015). "Remarkably, PARP14 is overexpressed in early stages of HCC and, importantly, its high expression is maintained during cancer progression, indicating that PARP14 upregulation might be required for both the formation and maintenance of HCC." (PMID 26258887, 2015). "Recent developments in enzymatic approaches to obtain ADP-modified peptides by PARP6, PARP3, PARP14, and PARP10 in human and murine diseases are advancing our ability to generate site-specific MAR antibodies, with future application in animal models of cancer and neurodegenerative diseases." (PMID 41463260, 2025). "In addition to PARP7 and PARP14, other MARylation enzymes, including PARP3, PARP8, PARP10, PARP11,142 as well as an ARTC family member, ARTC1,162 have been proposed as potential targets in cancer therapies." (PMID 37832523, 2023). "However, whether the survival function of PARP14 contributes to the Warburg effect in human cancer cells have not been previously investigated." (PMID 26258887, 2015).